FTO (FTO alpha-ketoglutarate dependent dioxygenase)
Diseases named in the same sentence as FTO in open-access papers (continued):
Sharing a sentence is not in itself a finding about the gene and the disease.
tumor (continued). "We analyzed the expression data of FTO in LUAD samples and found that FTO was also down-regulated in tumor samples than normal tissues, which were demonstrated in other two independent datasets incorporating GSE81809 (N = 199) and GSE68465 (N = 443)." (PMID 35945194, 2022). "Compared to the normal tissue, we found almost all ALKBH homologous were associated with tumor stage except ALKBH5 and FTO." (PMID 35980268, 2022). "Conversely, EZH2 was reported to enhance H3K27me3 and inhibit FTO expression in LUAD, indicating that FTO is a tumor suppressor in LUAD." (PMID 35945194, 2022). "As the first m6A demethylase identified to be dysregulated in various tumours, FTO is upregulated in pancreatic, gastric, and bladder cancers and promotes tumour growth and metastasis." (PMID 36358640, 2022). "The results showed that FTO overexpression resulted in a decrease in tumor volume from day 0 to day 21 and significant weight loss." (PMID 37529797, 2022). "We observed that decreased FTO expression inhibited tumor growth (volume and weight) and Ki67 staining in orthotopic transplantation models in B-NDG mice." (PMID 36263177, 2022). "The results presented that the genetic alteration rates of ALKBH1-8/FTO in GBM tumor samples were 2.9%, 1.9%, 1.7%, 10%, 1.5%, 2.4%, 2.2%, 1% and 3%, respectively." (PMID 35371987, 2022). "In contrast, the mRNA expression levels of ALKBH7 and FTO were negatively correlated with tumor stage." (PMID 34150745, 2021). "The role of FTO in tumor development and prognosis is inconsistent among different types of cancers." (PMID 34218271, 2021). "Remarkably, when examining all tumor samples, FTO and ALKBH5 mRNA expression levels were positively correlated (rs = 0.4243, p < 0.001)." (PMID 34683137, 2021). "FTO was up-regulated in tumor tissues of female patients or advanced stage patients, compared with male or early-stage patients, respectively." (PMID 34544449, 2021). "To explore the effects of FTO on the growth of BCa cells in vivo, we established a tumor xenograft mouse model." (PMID 34499008, 2021). "The expression of ALKBH5 and FTO has been proved to be up-regulated in tumor tissues, which implies a poor prognosis of HCC patients." (PMID 34557360, 2021). "The expression of CDK6 in the tumours injected with FTO-overexpressing cells increased significantly compared to those injected with control cells (NC), while opposite results were obtained in the FTO-knockdown group." (PMID 34725345, 2021). "We further investigated the effect of FTO expression on tumor metastasis in vivo through two metastasis models with luciferase-labeled HCT116 cells." (PMID 34218271, 2021). "FTO can inhibit the self-renewal of ovarian CSCs and inhibit the occurrence of tumours in vivo, both of which depend on the activity of FTO demethylase." (PMID 34794452, 2021). "Some studies have shown that FTO affects tumour progression via regulating microRNA (miRNA) expression." (PMID 34725345, 2021). "As expected, FTO depletion-enhanced tumor metastasis in the lung was also inhibited by c-Myc depletion." (PMID 33966037, 2021). "Among them, DDIT3 which is an apoptosis-related tumor suppressor gene was found to be up-regulated with the down-regulation of FTO." (PMID 33393595, 2021). "This is contradictory with our data that connects reduced FTO expression with enhanced chemoresistance and tumor initiation, as emphasized by our results from cell lines derived from CTCs, the source of lethal metastases." (PMID 33741917, 2021). "CRC cell lines with FTO overexpression had a significantly lower tumor growth rate and tumor weight." (PMID 34218271, 2021). "FTO, a member of demethylase, has been recognized as a key enzyme in the regulation of tumor occurrence, development, and progression." (PMID 34378866, 2021). "A recent study has found that some FTO inhibitors have been identified to play a role in tumor immunotherapy by interfering with RNA methylation." (PMID 33777035, 2021).
tumor (continued). "Restoration of FTO expression resulted in the upregulation of tumor spheres formation rate and related transcriptional factors of MHCC97HAMKD cells." (PMID 33783988, 2021). "Recent studies have revealed m6A methylation components can act as tumor-associated factors, including “writers” (METTL3/14, WTAP and KIAA1429), “erasers” (FTO and ALKBH5), and “readers” (YTHDF1/2/3, HNRNPA2B1, BCDIN3D)." (PMID 33791305, 2021). "Depletion of FTO enhanced tumor cell proliferation, anchorage-independent growth, migration, invasion, and tumor formation in mice." (PMID 33966037, 2021). "The FTO inhibitor Dac51 can inhibit FTO-mediated demethylation, inhibit the glycolytic ability of tumor cells, increase T cell infiltration, and have a synergistic effect with anti-PD-L1 therapy." (PMID 34616403, 2021). "Decreased m6A level by knockdown of the expression of METTL3 and/or METTL14 or overexpression of the eraser FTO can significantly accelerate tumorigenesis, specifically promoting the growth of human GSCs, as well as their self-renewal and tumor progression." (PMID 34381710, 2021). "In the present study, we assessed the tumor-inhibitory effects of FTO via m6A RNA methylation on BCa cells, and attempted to figure out a novel regulatory mechanism of post-transcriptional modification on gene expression in BCa progression." (PMID 34499008, 2021). "In previous studies, FTO and microRNA genes were demonstrated to be capable of interacting with and affect each other in adipose and tumor tissues, thus regulating adipogenesis and tumorigenesis." (PMID 33634966, 2021). "FTO gene knockout inhibits tumour growth and proliferation in vivo and induces G0/G1 cell cycle arrest." (PMID 34246319, 2021). "H&E staining and IHC staining against FTO demonstrated the positive correlation of FTO expression level and tumor malignancy." (PMID 33879631, 2021). "We next screened these genes for overlap with a list of 84 human tumor metastasis-related genes and identified four genes as potential downstream target genes of FTO." (PMID 34218271, 2021). "To connect FTO levels with in vivo tumor initiation potential we inoculated immunodeficient mice (athymic nude) with increasing numbers of sh-FTO or sh-CTL cells." (PMID 33741917, 2021). "Remarkably, as few as hundred sh-FTO cells were capable of initiating tumor formation in 4/5 mice vs. 1/5 for sh-CTL cells." (PMID 33741917, 2021). "FTO gene expression increased after intake of macronutrients such as carbohydrates and proteins that play a key role in the tumour formation process." (PMID 34650918, 2021). "Consistently, NEDD4L knockdown also partially reversed the effect of FTO deletion on tumor growth in vivo." (PMID 33846348, 2021). "Immunohistochemistry (IHC) staining of the tumor tissues showed that FTO depletion increased expression of c-Myc, HK2." (PMID 33966037, 2021). "More importantly, to further investigate the role of FTO in the regulation of the interaction between tumors and immune cells in tumor microenvironment, a mouse model with full immunocompetence (e.g., C57B/6 mouse strain) is needed in future studies." (PMID 34378866, 2021). "In the subcutaneous xenograft tumour model, the growth of tumours injected with FTO knockdown T24 cells was obviously inhibited." (PMID 34725345, 2021). "FTO was downregulated in tumor tissues, with discrepancies between the RNA and protein expression levels." (PMID 34218271, 2021). "CS1 and CS2 increased the m6A level, while it decreased cell growth, tumor growth, and tumor weight, supporting the anti-tumor effects of these FTO inhibitors in As-T cells." (PMID 33846348, 2021). "In the orthotopic tumor model, FTO overexpression reduced intestinal mesenteric metastasis and liver metastasis in mice bearing HCT116 cells." (PMID 34218271, 2021). "The effects of the FTO expression on tumor progression and malignancy were studied in HT‐1197 and HT‐1376 cells in vitro." (PMID 34499008, 2021).
tumor (continued). "It appeared that IGF2BP1/3, ELAVL1, HNRNPA2B1, HNRNPC, KIAA1429, RBM15, LRPPRC, FMR1, YTHDF1/2 are highly expressed in the tumor while FTO, METTL14/16, WTAP, YTHDC1 and ZC3H13 are down-regulated." (PMID 35095993, 2021). "In terms of immunotherapy, knockout of FTO gene expression can increase the sensitivity of tumour cells to immunotherapy." (PMID 34246319, 2021). "Targeting FTO genetically or pharmacologically inhibits the tumorigenicity of arsenic-transformed tumor cells." (PMID 33846348, 2021). "Such FTO upregulation is required for arsenic-induced tumorigenesis, as FTO deletion diminished arsenic-induced tumorigenesis in both a xenograft tumor model and an arsenic-UVB co-carcinogenesis model." (PMID 33846348, 2021). "Hepatocyte-specific depletion of FTO not only impacts HCC initiation phase (increased tumor numbers) but also influences HCC development (increased numbers of larger tumors) by inhibiting Cul4a translation." (PMID 33390849, 2021). "Then, we revealed that FTO inhibited tumor metastasis and progression in vitro and in vivo by decreasing the expression of its downstream target gene, metastasis-associated protein 1 (MTA1)." (PMID 34218271, 2021). "Consistently, RIP analyses with an anti-FTO antibody showed that FTO bound to MYC mRNA in the tumor cells." (PMID 33966037, 2021). "In the subcutaneous xenograft tumour model, the growth of tumours injected with FTO-overexpressing T24 cells was obviously promoted compared with those injected with control cells." (PMID 34725345, 2021). "Loss- and gain-of-function experiments established an inhibitory role of FTO in self-renewal ability, colony formation ability, spheroid formation ability in vitro, and also the tumour initiation capacity in vivo." (PMID 34895230, 2021). "Consistent with these discoveries regarding m6A levels, ALKBH5 and FTO were impaired to elevate m6A modification of targeted genes and accelerate tumour progression." (PMID 34895230, 2021). "Guanine nucleotide-binding protein G (o) subunit alpha (GNAO1) was identified as the downstream target of FTO and a tumor suppressor in HCC." (PMID 34421350, 2021). "In OC, dysregulation of ALKBH5 and FTO takes part in proliferation, apoptosis, migration, drug resistance, cancer stem cell development and tumour autophagy, contributing to the relapse of OC patients." (PMID 34895230, 2021). "Upregulation of FTO in CAL27‐A‐shRNA tumor compared to CAL27‐shRNA tumor and downregulation of FTO in CAL27‐A‐shFTO tumor compared to CAL27‐A‐shRNA tumor were confirmed by immunohistochemistry staining." (PMID 34378866, 2021). "We then explored mRNA expression of the several players among different tumor subtypes and found that erasers, FTO and ALKBH5, were expressed at higher levels, compared to writers." (PMID 34683137, 2021). "Next, epigenetic analysis via LC-MS/MS reveals higher m6A-abundance in ALKBH5-deficient as compared to FTO-deficient B16 tumours, which meaningfully suppresses the expression of m6A-mediated ‘Mct4/Slc16a3’ in ALKBH5 alone and ‘Mex3d’ in ALKBH5 and FTO both." (PMID 34571899, 2021). "To verify the expression pattern of FTO, we performed an immunohistochemical (IHC) staining assay to analyze its protein expression level in 240 paired tumor and adjacent normal tissues from SYSUCC CRC patients." (PMID 34218271, 2021). "We revealed a novel regulatory mode of RNA demethylase FTO degradation exerted by the tumor hypoxic microenvironment, indicating that FTO is a promising predictive factor for CRC metastasis." (PMID 34218271, 2021). "Some small-molecule inhibitors, such as inhibitors of the demethylase FTO, have been applied to treat tumors, implying the potential value of reversing m6A methylation in anti-tumor treatment." (PMID 34281602, 2021).
tumor (continued). "In fact, an oncogenic role of FTO has been suggested by multiple studies, in which FTO was reported to positively influence proliferation and survival of tumor cells but inhibit cell death and differentiation in various types of human cancer cells." (PMID 33634966, 2021). "For MDA-MB-231, MCF-7 and 4 T1 breast cell lines, upregulated FTO promotes tumour proliferation and metastasis or reduces cell apoptosis by targeting BNIP3." (PMID 34044876, 2021). "In OC, FTO plays a tumor suppressor role and impairs ovarian cancer stem cells (OCSCs) function when overexpressed." (PMID 34586737, 2021). "We demonstrated that FTO protein is however, highly expressed in tumor tissues and cells due to the upregulation of USP18." (PMID 33461172, 2021). "Regarding tumor stemness, in this study, YTHDF2, HNRNPA2B1, HNRNPC, IGF2BP1, and KIAA1429 were positively correlated with tumor stemness, while FTO was negatively correlated with tumor stemness." (PMID 35003079, 2021). "FTO induces tumor progression by targeting MZF1, reducing the m6A in MZF1 transcript, increasing the stability and thus increased expression of MZF1 mRNA." (PMID 32194861, 2020). "The same situation also exists in METTL14 and FTO, both of which show low expression in tumor tissues." (PMID 32258108, 2020). "Knockdown of FTO suppressed the proliferation and in vivo tumor growth, and induced the G0/G1 phase arrest." (PMID 33304380, 2020). "In 4T1 cells, BNIP3 knockdown significantly weakened FTO-accelerated tumor growth and metastasis in a subcutaneous implantation model and tumor metastasis model in Balb/c mice." (PMID 33505967, 2020). "FTO facilitates the proliferation and in vivo tumor growth via demethylating of PKM2 mRNA and enhancing its translation efficiency." (PMID 33372610, 2020). "R-2-hydroxyglutarate (R-2HG), a tumor suppressor, can inhibit the expression of FTO, providing us a novel imagination in AML treatment." (PMID 32612834, 2020). "We found that METTL14 and RBM15B mRNA expression significantly decreased, while FTO significantly increased in tumor tissues." (PMID 31159832, 2019). "Further, we demonstrated that ALKBH3 and FTO levels are correlated with primary tumour size (T in TNM classification): protein expression was higher in larger T4 tumours, as compared to smaller T2 tumours." (PMID 31519943, 2019). "The low expression of FTO in human ccRCC correlates with increased tumour severity and poor patient survival." (PMID 30648791, 2019). "The data presented here show that FTO, a member of the AlkB subfamily of FeII/α‐ketoglutarate‐dependent dioxygenases and the first identified m6A demethylase, act as a tumour suppressor in ccRCC." (PMID 30648791, 2019). "We detected significantly higher levels of ALKBH3 and FTO in larger primary tumours (type T4 in TNM classification), as compared to smaller ones (type T2 in TNM classification)." (PMID 31519943, 2019). "Knockdown of FTO markedly reduced tumor volume and tumor growth in both Mel624 and CHL-1 cells in immunocompromised nude mice, and in B16F10 cells in immunocompetent C57BL/6 mice." (PMID 31239444, 2019). "At 30 days after injection, all mice bearing FTO-knockdown cells barely had detected tumors whereas mice bearing control cells showed visible tumor growth as reflected by the luciferase signals in vivo." (PMID 30922314, 2019). "Mechanistically, we identified FTO as a direct target of R-2HG and a main mediator of R-2HG-induced anti-tumor effects." (PMID 29686311, 2018). "The functional importance of FTO in tumor progression has also been revealed in lung squamous cell carcinoma (LUSC)." (PMID 30149601, 2018). "When looking at FTO expression between normal and tumor tissue we found that the FTO in tumor tissue was significantly lower than in normal tissue (p-value < 0.001)." (PMID 21489227, 2011). "Additionally, FTO-driven m6A modification of circGDI2 increased its expression, whereas silencing FTO suppressed HCC tumor growth and decreased circGDI2, IGF2BP2, and PKM2." (PMID 41439029, 2026).
tumor (continued). "RT-qPCR showed that FTO level was significantly increased in tumor tissues." (PMID 41439029, 2026). "IHC suggested that FTO knockdown reduced the number of Ki-67 positive cells, Tunel staining results indicated that interfering with FTO expression promoted the level of apoptosis in tumor tissues." (PMID 41439029, 2026). "In vivo studies demonstrated that overexpression of FTO promotes tumor growth in TNBC cells." (PMID 42264087, 2026). "FTO knockdown significantly suppressed the tumor weight and volume." (PMID 41439029, 2026). "HE staining showed that FTO knockdown led to disrupted tumor tissue." (PMID 41439029, 2026). "Study shows that tumor matrix stiffening can activate mammalian target of rapamycin 1 (mTORC1) and achieve cell death resistance under matrix detachment through the integrin-glycogen synthase kinase 3 beta (GSK3β)-FTO-mTOR axis." (PMID 40356596, 2025). "To elucidate how FTO supports tumor growth, we determined whether FTO inhibition or knockdown influences cell proliferation and cell migration/expansion." (PMID 40722726, 2025). "The FTO gene, which is involved in fat metabolism, may contribute to the development and progression of oral cancer by influencing tumor cell metabolism and inhibiting the expression of tumor suppressor genes." (PMID 40282437, 2025). "FTO is primarily localized in the nucleus and cytoplasm, and co‐localization studies with the proliferation marker Ki67 suggest a potential regulatory interaction contributing to tumor cell proliferation." (PMID 41141648, 2025). "Furthermore, FTO was found to be overexpressed in late-stage NSCLC tumor tissues compared to early-stage tumors, and it was upregulated in patients who smoked." (PMID 40722726, 2025). "However, current therapeutic strategies predominantly focus on regulating the tumor microenvironment, neglecting the full potential of FTO inhibitors in combinatorial approaches." (PMID 41281757, 2025). "More current studies have suggested FTO could suppress tumor growth, potentiate immunotherapy, and overcome drug resistance." (PMID 40722726, 2025). "On the other hand, targeting m6A “erasers” such as ALKBH5 or FTO, which regulate immune checkpoint molecule expression by demethylating m6A modifications, could suppress immune suppression and promote anti-tumor immune responses." (PMID 39911396, 2025). "Therefore, our work highlighted the crucial roles of the SRSF6/FTO feedback loop in tumor cell ferroptosis resistance and tumor progression, which provided potential therapeutic targets for antitumor treatment." (PMID 40712780, 2025). "Our study could be expanded by examining the mechanisms by which FTO affects tumor growth, such as FTO’s effect on cell metabolism and energy balance in tumorigenesis." (PMID 40722726, 2025). "FTO is also recognized as an anti-tumor target with great promise." (PMID 40483535, 2025). "Since smokers are more likely to have a high expression of FTO, this suggests these patients might be more prone to drug resistance and tumor growth." (PMID 40722726, 2025). "This broad expression suggests that tumor-selective FTO degradation induced by FP54 may have notable clinical benefits." (PMID 40815637, 2025). "An in vivo subcutaneous xenograft model was used to validate the tumor-suppressive role of FTO." (PMID 40970086, 2025). "These bioinformatic predictions suggest that FTO may exert its tumor-suppressive effects by modulating cell proliferation via the PI3K/Akt pathway." (PMID 40970086, 2025). "The expression of FTO in tumor cells is lower than that in normal cells." (PMID 40830264, 2025). "Hence, defining the distinct demethylation substrate RNA molecules of FTO across multiple tumor types will be informative in the future." (PMID 41184232, 2025). "Previous studies have reported that FTO has different roles in various cancers, exhibiting both tumor-promoting and tumor-suppressing effects, suggesting that the role of FTO in cancer may be dependent on its microenvironmental context." (PMID 40819127, 2025).